SOX2-OT (SOX2 overlapping transcript)
Diseases named in the same sentence as SOX2-OT in open-access papers (continued):
Sharing a sentence is not in itself a finding about the gene and the disease.
cancer (continued). "Enforced SOX2OT expression was predictive of unfavorable OS (HR = 2.44, 95% CI: 1.75–3.39, P<0.0001) and tumor progression (III/IV vs. I/II: HR = 1.62, 95% CI: 1.30–2.02, P<0.0001) in various carcinomas with multivariate analysis, respectively." (PMID 28489861, 2017). "Furthermore, cancer associated genes (e.g., ROCK2, NFKB) are also significantly correlated with SOX2OT in SAGE libraries; which highlighted the potential function of SOX2OT in cancer progression." (PMID 26136768, 2015). "Close concomitant expression patterns of SOX2OT and SOX2 in stem cells and some human cancers, have all suggested that they may be co-regulated and involved in similar molecular pathways." (PMID 26136768, 2015). "In this review, we have delineated the complex structure and functional features of SOX2OT locus, with more emphasis on its expression and splicing patterns, and its potential role in the regulation of SOX2 expression during the development and cancer progression." (PMID 26136768, 2015).
tumor (29 papers, 2014 to 2023). "Using qRT-PCR, we initially examined the expression pattern of newly identified human SOX2OT variants (transcripts 1/4/6/7/8) in 6 OS tumor tissue mixture, with specific primers for each variant." (PMID 29475441, 2018). "The relative expression of the two most abundantly expressed SOX2OT variants (transcripts 1 and 7) were measured in OS tumor tissues and their responding adjacent tissues (n = 6) by qRT-PCR." (PMID 29475441, 2018). "Different studies have shown that SOX2OT acts as an oncogene and is elevated in different tumor types." (PMID 37218885, 2023). "The increased expression of SOX2OT was detected in glioma tissues, and its expression was positively correlated with the tumor grade." (PMID 37047365, 2023). "Previous studies support overexpression of SOX2OT in tumor tissues of the breast, esophageal, lung, and hepatocellular." (PMID 36548179, 2022). "Recent studies have demonstrated that SOX2OT is overexpressed in many cancers and involved in tumor development and progression by acting as an oncogene to promote cell proliferation, invasion, migration, and growth and suppress cell apoptosis." (PMID 34760707, 2021). "They found that the tumor suppressor YY1 bound to the promoter of SOX2OT and inhibited tumor growth in vivo and in vitro by suppressing SOX2OT and SOX2 expression in PC." (PMID 34760707, 2021). "Overexpressed SOX2OT also increased levels of pluripotent transcription factors related to tumor chemoresistance, whereas knocking down its expression presented the opposite effect." (PMID 32439916, 2020). "As SOX2OT has a variety of transcript isoforms that play different roles in tumor progression, sequencing should be performed to further identify the functional isoforms." (PMID 29504701, 2018). "An in vivo tumor model was used to further determine the functions of SOX2OT, miR-194-5p and miR-122." (PMID 29132362, 2017). "After embryonic development, SOX2OT is abnormally expressed in many diseases and plays an important role in the regulation of malignant biological behavior of many tumors and is closely related to the prognosis of tumor patients." (PMID 33993197, 2021). "For example, SOX2OT is highly expressed in ESCC tumor tissues." (PMID 31235759, 2019). "Nevertheless, neither SOX2OT expression nor SOX2 expression was associated with ESCC tumor size, lymphatic metastasis, N stage, M stage and prognosis." (PMID 29849506, 2018). "Overexpression of SOX2OT promotes tumor growth and metastasis and correlates with poor prognosis." (PMID 29849506, 2018). "We established a diagnostic panel consisting of lncRNA (SOX2OT and ANRIL) and tumor markers (CEA, CYFRA21‐1, and SCCA), which could diagnose NSCLC with superior sensitivity and specificity." (PMID 29504701, 2018). "The expression of SOX2 and SOX2OT was found to be significantly up-regulated in tumor xenografts." (PMID 25006803, 2014). "Moreover, SOX2 and SOX2OT expression levels were correlated with stage of tumor." (PMID 31956395, 2020). "Previous evidence has illuminated that AKT2 was targeted and negatively mediated by miR-194, and the upstream lncRNA SOX2OT served as a miR-194 sponge to upregulate AKT2, intensifying tumor growth and metastasis of GC30." (PMID 34548487, 2021). "LncRNAs known to be a regulatory factor of tumor stem cells included GAS5, NEAT1, SOX2OT, Malat-1, HOTAIR, PVT1, BCAR4 and RBM5-AS1." (PMID 31143372, 2019). "Furthermore, SOX2OT may regulate cell migration and invasion of multiple tumor cells." (PMID 31827385, 2019). "qPCR was performed to determine the RNA expression of SOX2OT and SOX2 in the ESCC and adjacent non-tumor tissues." (PMID 29849506, 2018). "Univariate Cox proportional hazards regression model analysis revealed a statistically significant correlation between the OS rate of NSCLC patients and SOX2OT level (P = 0.009), ANRIL level (P = 0.019), tumor size (P < 0.001), lymph node metastasis (P < 0.001), and TNM stage (P < 0.001)." (PMID 29504701, 2018).
SOX2-OT also shares sentences with these, for which no sentence is quoted: non-small cell lung carcinoma (3 papers); Huntington disease (2); liver cancer (2); lung adenocarcinoma (2); Parkinson disease (2); adenocarcinoma (1); anorexia nervosa (1); breast invasive carcinoma (1); cervical cancer (1); Cognitive impairment (1); colorectal cancer (1); embryonal carcinoma (1); lentivirus infection (1); metastatic tumours (1); prostate carcinoma (1); rectal cancer (1); renal fibrosis (1); tongue squamous cell carcinoma (1); urothelial carcinoma of the bladder (1).